CACNG3 (calcium voltage-gated channel auxiliary subunit gamma 3)
Description:
Regulates the trafficking to the somatodendritic compartment and gating properties of AMPA-selective glutamate receptors (AMPARs). Promotes their targeting to the cell membrane and synapses and modulates their gating properties by slowing their rates of activation, deactivation and desensitization. Does not show subunit-specific AMPA receptor regulation and regulates all AMPAR subunits. Thought to stabilize the calcium channel in an inactivated (closed) state.
Tractability: Small molecule: an approved drug acts on it; a high-quality ligand is known; it belongs to a druggable protein family. Antibody: its Gene Ontology location is reachable by antibodies, with high confidence; UniProt predicts a signal peptide or a membrane-spanning region.
Gene: Protein-coding gene on chromosome 16 (24,256,286 to 24,362,412, forward strand). Ensembl gene ENSG00000006116.
Subcellular location: Membrane
Pathways (Reactome):
Developmental Biology: LGI-ADAM interactions
Neuronal System: Trafficking of AMPA receptors
Gene Ontology:
Molecular function: channel regulator activity; voltage-gated calcium channel activity; ionotropic glutamate receptor binding; PDZ domain binding
Biological process: calcium ion transport; intracellular protein localization; positive regulation of synaptic transmission, glutamatergic; postsynaptic neurotransmitter receptor diffusion trapping; protein targeting; regulation of AMPA receptor activity; transmission of nerve impulse; calcium ion transmembrane transport; neurotransmitter receptor localization to postsynaptic specialization membrane
Cellular component: AMPA glutamate receptor complex; endocytic vesicle membrane; plasma membrane; postsynaptic density membrane; somatodendritic compartment; voltage-gated calcium channel complex; dendrite; excitatory synapse; glutamatergic synapse; membrane; organelle; Schaffer collateral - CA1 synapse
Genetic constraint (gnomAD): Loss-of-function variants: 3 observed, 26.2 expected, observed/expected ratio (o/e) 0.11, 90% interval 0.051 to 0.3. The upper end of that interval is the gene's LOEUF score, 0.3, which puts it in group 1 of 6, group 1 being the genes least tolerant of losing a copy. Missense variants: 230 observed, 416.72 expected, observed/expected ratio (o/e) 0.55, 90% interval 0.5 to 0.62. Synonymous variants: 166 observed, 162.62 expected, observed/expected ratio (o/e) 1.02, 90% interval 0.9 to 1.16.
Homologues: Orthologues: chimpanzee CACNG3 (100% identical), macaque CACNG3 (100% identical), dog CACNG3 (99% identical), pig CACNG3 (99% identical), guinea pig CACNG3 (99% identical), rabbit CACNG3 (99% identical), mouse Cacng3 (99% identical), rat Cacng3 (99% identical), tropical clawed frog cacng3 (84% identical), zebrafish cacng3b (80% identical), Caenorhabditis elegans stg-2 (20% identical). Paralogues in human: CACNG2 (76% identical), CACNG4 (60% identical), CACNG8 (60% identical), CACNG7 (28% identical), CACNG5 (28% identical).
Diseases named in the same sentence as CACNG3 in open-access papers:
CACNG3 is named in the same sentence as 14 diseases in open-access papers, as found by Europe PMC text mining. Sharing a sentence is not in itself a finding about the gene and the disease. The quoted sentences say what the papers report.
childhood absence epilepsy (2 papers, 2017 to 2022). A familial generalized pediatric epilepsy, characterized by very frequent (multiple per day) absence seizures, usually occurring in children between the ages of 4 and 10 years, with, in most cases, a good prognosis. "Further, CACNG3 is the best candidate for age-related macular collapse and is susceptible to childhood absence epilepsy (CAE)." (PMID 35958988, 2022). "CACNG3 is involved in Childhood Absence Epilepsy and is also associated with some cases of ASD while mutations of KATNB1 cause complex cerebral malformations." (PMID 28993790, 2017).
epilepsy (2 papers, 2020 to 2023). A brain disorder characterized by episodes of abnormally increased neuronal discharge resulting in transient episodes of sensory or motor neurological dysfunction, or psychic dysfunction. "As a member of the voltage-gated calcium channel gamma subunit gene (CACNG) family, previous studies have reported the role of CACNG3 in downregulating calcium channel activity, which associates with numerous neurological disorders, especially seizure disorders." (PMID 37697240, 2023).
brain tumor (1 paper, 2023). "Surprisingly, alterations in ion channel activity are linked to genetic mutations of tumor suppressors and oncogenes in most brain tumor cases, suggesting that up-or down-regulation of CACNG3 may also relate to these encoding genes." (PMID 37697240, 2023). "However, the role and function of CACNG3 in brain tumors are still unclear." (PMID 37697240, 2023).
glioma (1 paper, 2023). A benign or malignant brain and spinal cord tumor that arises from glial cells (astrocytes, oligodendrocytes, ependymal cells). "The results showed that CACNG3 expression was significantly associated with glioma grades, as gene expression decreased in higher-grade gliomas." (PMID 37697240, 2023). "The enrichment results suggest that these negatively impacted genes associated with CACNG3 in gliomas may remodel the tumor microenvironment of glioma cells and promote immune escape." (PMID 37697240, 2023). "Furthermore, CACNG3 expression was negatively associated with glioma grades, which was confirmed in the IHC results of clinical samples." (PMID 37697240, 2023). "From this perspective, we conducted further analysis to explore the correlation between CACNG3 expression and clinical parameters to determine its potential mechanisms of mediating glioma progression." (PMID 37697240, 2023). "From this perspective, we conducted further analysis to explore the possible role and function of CACNG3 in gliomas." (PMID 37697240, 2023). "Meanwhile, by studying the influence of CACNG3 expression on the overall survival of glioma patients, we assessed its prognostic value in gliomas." (PMID 37697240, 2023). "Further research on the interplay among the DEGs is needed to determine the exact mechanism by which CACNG3 influenced the development of gliomas." (PMID 37697240, 2023). "By conducting biologic function analyses of 330 genes positively related to CACNG3 expression, retrieved through correlation analysis using CGGA datasets, we concluded that CACNG3 affected glioma cells by modulating synaptic transmission." (PMID 37697240, 2023). "In our study, we preliminarily explored differently expressed genes between the tumor group and the normal group, using gene data extracted from the CGGA RNA-seq set and GSE 4290 array set, and observed significantly lower CACNG3 expression in gliomas." (PMID 37697240, 2023). "CACNG3 expression and related clinical data were collected from three major databases of The Chinese Glioma Genome Atlas (CGGA), The Cancer Genome Atlas (TCGA), and Gene Expression Omnibus (GEO)." (PMID 37697240, 2023). "Given the significant relationship between CACNG3 expression and the malignancy of gliomas, we further analyzed genes positively related to CACNG3 expression by performing the Pearson correlation analysis in the CGGA and TCGA datasets." (PMID 37697240, 2023). "The CACNG3 expression in different glioma grades was further analyzed by conducting the Kruskal-Wallis rank-sum test." (PMID 37697240, 2023). "Both IHC and WB results were consistent with previous results that CACNG3 expression decreased in higher-grade gliomas." (PMID 37697240, 2023). "In this study, we analyzed the role and function of CACNG3 in gliomas for the first time and provided a basis for following clinical studies on CACNG3 in gliomas." (PMID 37697240, 2023). "Next, univariate and multivariate based on the Cox proportional hazards model were carried out in CGGA datasets to evaluate the prognosis value of CACNG3 expression in gliomas of all grades." (PMID 37697240, 2023). "The purpose of this study is to explore CACNG3 as a prognostic factor that is closely related to the progression and survival outcome of gliomas and to provide a potential new molecular target for the diagnosis and treatment of glioma patients." (PMID 37697240, 2023). "Therefore, CACNG3 plays a vital role in the occurrence and development of gliomas and can serve as a potential biomarker for targeted therapy and further investigation in the future." (PMID 37697240, 2023). "CACNG3 could inhibit glioma growth, as CACNG3 overexpression decreased the proliferation markers of the tumor (Ki67 and PCNA)." (PMID 37697240, 2023). "As for cell experiments, temozolomide, a chemotherapeutic drug for glioma, could increase CACNG3 expression in concentration and time dependence." (PMID 37697240, 2023).
glioma (continued). "Furthermore, survival analysis revealed that CACNG3 had a positive influence on the overall survival of glioma patients." (PMID 37697240, 2023). "In addition, clinical and molecular features, including WHO Grade II and neural subtypes were enriched in gliomas with high CACNG3 expression, which is consistent with previous results." (PMID 37697240, 2023). "In this research, we hypothesized that CACNG3 is related to the occurrence and malignancy of gliomas." (PMID 37697240, 2023). "To confirm this finding and further explore the predictive ability of CACNG3 as a potential biomarker, we performed the receiver operating characteristic curve (ROC) for CACNG3 expression and both mesenchymal and neural molecular subtypes of all grade gliomas." (PMID 37697240, 2023). "In addition, the univariate and multivariate analysis verified the prognostic value of CACNG3 in predicting the OS of gliomas of all grades." (PMID 37697240, 2023). "The results indicated that these genes could have inhibited the expression of CACNG3 and remodeled the tumor microenvironment of glioma cells, thus promoting the development of glioma cells." (PMID 37697240, 2023). "The results of functional annotation and pathway enrichment analysis of differently expressed genes(DEGs), showed that CACNG3 might affect the development of glioma by interfering with synaptic transmission." (PMID 37697240, 2023). "We assessed the ability of CACNG3 to be a prognostic marker and a biomarker of different glioma molecular subtypes, which may provide novel insights into the diagnosis and treatment of gliomas." (PMID 37697240, 2023). "Our results showed that CACNG3 expression gradually decreased with the increase of glioma grades." (PMID 37697240, 2023). "Moreover, temozolomide (TMZ), commonly used in the treatment of glioma, increased CACNG3 expression in a dose and time-dependent manner." (PMID 37697240, 2023). "Next, we investigated the influence of CACNG3 on the overall survival of glioma patients." (PMID 37697240, 2023). "The results of COX analysis suggested that CACNG3 could serve as a prognostic factor in glioma." (PMID 37697240, 2023). "As is shown in GO function analysis results of co-expression genes of CACNG3, the main molecular function of these genes is to regulate ion channel activity, and the transmembrane ion flux mediated by ion channels relates to the regulation of tumor progression, especially in gliomas." (PMID 37697240, 2023). "Moreover, IHC results of clinical samples also showed low CACNG3 expression in grade IV gliomas." (PMID 37697240, 2023). "If CACNG3 can be interfered with in the body, CACNG3 may act as a novel target of glioma therapy." (PMID 37697240, 2023). "Therefore, as had been concluded in functional annotation results, CACNG3 may inhibit the development of gliomas by modulating synaptic transmission and other biological processes related to the malignancy of gliomas." (PMID 37697240, 2023). "Furthermore, we suggested that CACNG3 could serve as a potential biomarker, which may provide novel insights into the diagnosis and treatment of gliomas." (PMID 37697240, 2023). "Furthermore, CACNG3 may play a critical role in the regulation of synaptic transmission and ion channel activity which inhibits the occurrence and development of gliomas." (PMID 37697240, 2023). "In addition, univariate and multivariate analyses indicated that CACNG3 could serve as an independent prognostic factor in gliomas." (PMID 37697240, 2023). "The area under the curve (AUC) was 74.6% and 84.9% respectively in the CGGA datasets, which indicated that CACNG3 could serve as a potential biomarker of a mesenchymal and neural molecular subtype of the gliomas, while CACNG3 had a more significant ability in predicting neural molecular subtype." (PMID 37697240, 2023). "The results indicated that CACNG3 might play an important role in glioma." (PMID 37697240, 2023).
glioma (continued). "The results indicated that CACNG3 might play an important role in glioma treatment." (PMID 37697240, 2023). "Interstingly, CACNG3 overexpression decreased the expression of Ki67 and PCNA, the proliferation markers of the tumor, which suggests CACNG3 could inhibit glioma growth." (PMID 37697240, 2023). "As the mesenchymal transition of glioma cells correlates with a more invasive and treatment-resistant phenotype, indicating poor prognosis and recurrence in patients with GBM, down-regulated CACNG3 in the mesenchymal molecular subtype suggests a poor prognosis." (PMID 37697240, 2023).
cancer (2 papers, 2017 to 2023). A tumor composed of atypical neoplastic, often pleomorphic cells that invade other tissues. "Additionally, in light of the relationship between CACNG3 and the DEGs and the important function of these genes in various cancers, further experiments are needed to explore the interaction between these genes and how they possibly inhibit or promote tumor progression together." (PMID 37697240, 2023).
tumor (1 paper, 2023). "CACNG3 was expressed at low levels in the tumor group, and the overall survival (OS) in patients with low CACNG3 expression is shorter." (PMID 37697240, 2023). "Meanwhile, as is shown in the PPI network, among the DEGs positively related to CACNG3 expression, 6 members belong to the solute carrier proteins (SLC) superfamily of transporter proteins which enables specific molecules, including anti-tumor drugs, to enter or leave the cell." (PMID 37697240, 2023).
CACNG3 also shares sentences with these, for which no sentence is quoted: Anxiety (1 paper); astrocytoma (1); fragile X syndrome (1); glaucoma (1); lymphoma (1); malignant glioma (1); medulloblastoma (1); neurological disorders (1).